IL6 (interleukin 6)
Diseases named in the same sentence as IL6 in open-access papers (continued):
Sharing a sentence is not in itself a finding about the gene and the disease.
head and neck cancer (continued). "We also examined the STAT3 activation mediated through IL-6 in head and neck cancer." (PMID 24533098, 2014). "miR145 could target the SOX9/ADAM17 axis and inhibit tumor-initiating cells and IL-6-mediated paracrine effects in head and neck cancer." (PMID 24941171, 2014). "Furthermore, there are published studies from our group where increased serum IL-6 levels correlate with advanced head and neck cancer." (PMID 24533098, 2014). "IL-6 is one of the main chemokines present in serum samples of cancer patients and elevated IL-6 levels have been shown to be an independent predictor of tumor recurrence, poor survival and tumor metastasis in a number of malignancies including breast, prostate and head and neck cancers." (PMID 28978005, 2017). "Specific combinations of keywords were used, including salivary cytokines, interleukin-6 (IL-6), interleukin-8 (IL-8), epidermal growth factor (EGF), head and neck cancer, and radiotherapy." (PMID 41220465, 2025). "The head and neck cancer patients’ salivary cytokines that were assessed by the studies, along with photobiomodulation therapy, included IL-12p70, TNF-α, IL-6, IL-8, IL-10, CXCL8, and IL-1β." (PMID 38792366, 2024). "In a study by that longitudinally evaluated the saliva of patients with head and neck cancer undergoing treatment with RT and CRT, was showed an increase in cytokines IL-1β, IL-6 and TNFα in the saliva of patients who underwent CRT compared to RT." (PMID 38725825, 2024). "In head and neck cancer, FAP+ CAFs inhibited CD8+ T cell proliferation and promoted regulatory T cell (Treg) recruitment by secreting TGF-β and IL-6." (PMID 37480115, 2023). "It has been suggested that IL-6 induced macrophage expressed M1 macrophage marker, leading to an inflammatory TME thereby enhancing radiosensitivity in HPV+ head and neck cancer." (PMID 37127625, 2023). "By secreting TGF and IL6, -SMA+ FAP+ CAFs in head and neck cancer suppress the growth of CD8+ T cells and increase the recruitment of CD4+ CD25+ T cells." (PMID 36465405, 2022). "This is in line with reports that CAF-secreted IL-6 induces OPN, which itself is significantly upregulated in head and neck carcinomas and correlated with poor prognosis." (PMID 35903297, 2022). "The outliers of IL-6, IL-10 and TNF in the post-index group were detected in saliva samples from different patients with head and neck carcinoma, and all sampling time was at OM occurrence." (PMID 35476641, 2022). "In head and neck cancer, the inhibition of CD147 alleviates proinflammatory cytokines, e.g., IL-1β, IL-6, and IL-8, mediated cancer cell proliferation in vitro and in vivo." (PMID 34948304, 2021). "It has been demonstrated that IL-6 induces the expression of Snail through JAK/Stat3 signaling in cervical, colorectal or head and neck cancers." (PMID 32570756, 2020). "Corroborative findings on head and neck carcinoma patient serum post-PDT revealed an increase in HMGB-1, interleukin-6/10 (IL-6/10), which unfortunately correlated with a reduction in perforin, traducing the PDT immunomodulatory effects." (PMID 32899183, 2020). "In a recent study on a cohort of 32 patients with head and neck cancer treated with chemoradiotherapy IL-1β and TNF-α levels decreased 60 days after treatment as compared to the pre-treatment level whereas IL-6 levels increased." (PMID 31750257, 2019). "An invasion experiment recapitulating the oral mucosa showed that the suppression of TTP activity gives rise to an accelerated invasion rate of head and neck cancer cells due to the secretion of MMP-2, MMP-9, and interleukin-6 (IL-6)." (PMID 30380668, 2018). "In this study, we analyzed the immune regulatory properties of EGFR signaling in head and neck cancer cells and showed that it suppresses type 1 cytokine-induced expression of CCL2, CCL5, CXCL9, CXCL10 and IL-6 while promoting the expression of IL-1β." (PMID 30192802, 2018).
head and neck cancer (continued). "To examine the effect of IL-6 on PRMT5 nuclear localization, we performed nuclear/cytosolic fractionation and immunofluorescence staining experiments using head and neck cancer cell lines." (PMID 28107179, 2017). "Endothelial cell-secreted IL-6 induced EMT and enhanced migration in head and neck cancer stem cells." (PMID 29245982, 2017). "Significant differences in the circulating levels of serum IL-6, IL-8, IL-10, MCP-1 and IP-10 after three months of the nutritional intervention were observed in patients with head and neck cancer, neuroendocrine tumors, gastric, colon, urothelial or other types of cancer." (PMID 38892006, 2024). "Induction of IFNβ post-IR followed by the interplay of IFN-induced proteins (STAT1, ISG15) and cytokines (IL-1β, IL-6, MIF) hints towards IR-induced inflammation contributing to initiation and progression of oral mucositis that affects a majority of head and neck cancer patients." (PMID 37384298, 2023). "Similarly, IL-10 was shown to be upregulated in head and neck cancer and correlated with tumor progression via the JAK-STAT system, also inducing the expression of IL-6." (PMID 36143043, 2022). "Indeed, the other researchers had assessed the presence of salivary cytokines (e.g., IFN-γ, IL-1β, IL-6, IL-8, IL-10, TNF-α, VEGF) in patients with head and neck cancer (HNC)." (PMID 29515773, 2018). "We next examined if blockade of IL-6 signaling by BZA could reverse chemo and radioresistance in head and neck cancer cells." (PMID 28978005, 2017). "Interestingly, IL-6 can stimulate casein kinase 2 (CK2)-mediated phosphorylation and stabilization of Twist in head and neck cancer cells." (PMID 29088851, 2017). "However, the role of endothelial cell-secreted IL-6 on migratory behavior of head and neck cancer stem cells have not been investigated." (PMID 29245982, 2017). "Collectively, these results demonstrate that endothelial cell-secreted IL-6 induces a migratory phenotype in head and neck cancer stem cells and suggest that the progression of HNSCC towards metastasis or recurrence might be prevented or delayed by therapeutic blockage of the IL-6 pathway." (PMID 29245982, 2017). "Furthermore, IL-6 independent STAT3 activation can be found in other cancers, including head and neck cancers and haemopoietic cancers, suggesting that not all cancers that have high STAT3 activity necessarily have high IL-6 expression." (PMID 31226168, 2019).
septic shock (89 papers, 2005 to 2026). Shock caused by infection; frequently caused by gram negative bacteria, although some cases have been caused by other bacteria, viruses, fungi, and protozoa; characterized by fever, chills, tachycardia, tachypnea, and hypotension. "We demonstrated, for instance, that interleukin (IL)-6 plays an important role in the loss of contractile proteins in muscle fibers exposed to plasma from septic shock patients." (PMID 27091359, 2016). "The IL-6 rs1800795 CC genotype was associated with higher risk of septic shock-related death during the first 7 days [adjusted hazard ratio (aHR 4.65; p = 0.002), 28 days (aHR 2.50; p = 0.006), and 90 days (aHR 2.28; p = 0.006)] with septic shock." (PMID 28247301, 2017). "In patients with septic shock, a fall in IL-6 levels is associated with survival." (PMID 23028694, 2012). "In this clinically relevant septic shock model, mCBS treatment modulated the inflammatory response as shown by differences in systemic IL-6 and changes in H3.1 nucleosome levels." (PMID 38001494, 2023). "In septic shock patients, neutrophil counts, infection biomarkers (C-reactive protein, ferritin, and procalcitonin levels), and cytokines (IL-1β, IL-2R, IL-6, IL-8, IL-10, and TNF-α) increased significantly." (PMID 36845110, 2023). "Previous animal studies have shown that the P-gp inhibitor verapamil reduces the serum levels of inflammatory mediators (e.g., TNF-α and IL-6) and improves the survival rate of mice upon LPS-induced septic shock." (PMID 36482035, 2023). "Septic shock patients were characterized by an increased IL-6 and IL-8, increased myeloid activation biomarkers, endothelial activation biomarkers (except TF), a prolonged coagulation, increased D-Dimers, and platelets activation biomarkers." (PMID 35111777, 2021). "A prospective study on 72 septic shock patients showed that low ADAMTS13 activity correlated well to high interleukin-6 levels." (PMID 34819564, 2021). "In the LPS-induced murine septic shock model used in this study, the levels of IL-6, TNFα, MCP-1, and IL-10 increased 36 h after LPS administration, except IL-1β." (PMID 34066510, 2021). "Several studies on septic shock have reported that IL-6 and TNF-α levels are elevated and have a correlation between cytokines levels cytokines and mortality." (PMID 34493028, 2021). "The AUC to discriminate septic shock was 0.80 for IL-6 (95% CI, 0.71–0.89; P < 0.001), 0.70 for PTX3 (95% CI, 0.60–0.81; P < 0.001), 0.73 for PCT (95% CI, 0.63–0.83; P < 0.001), and 0.53 for CRP (95% CI, 0.42–0.65; P = 0.603)." (PMID 31718563, 2019). "The univariate analysis determined that the significant risk factors for 28-day mortality were IL-6, PTX3, lactate, SOFA and APACHE II scores, and septic shock." (PMID 31718563, 2019). "From the 46 septic shock patients admitted to our institution, follow-up samples were obtained from 28 patients within 24 h of discharge to measure IL-6 and PTX3, 15 of whom recovered, and 13 died." (PMID 31718563, 2019). "In these conditions, the level of IL-6 in plasma is consistently high, and it is correlated with various indicators of disease severity including multi-organ failure and septic shock and global mortality." (PMID 30142934, 2018). "A study with 70 septic shock patients demonstrated 64% detectability of IL-6 in sera at the study entry." (PMID 29769838, 2018). "Analysis of cytokine profiles following treatment revealed significant elevations in IL-6 and IL-10 in anti-HMGB1 pAb-treated mice 24 hours following surgery, which were both associated with survival in the septic shock patient cohort." (PMID 28724977, 2017). "Stress dose of hydrocortisone infusion in patients with septic shock significantly decreased plasma IL-6 levels on day 5 between the steroid and placebo groups." (PMID 27555669, 2016). "The serum concentration of pr-inflammatory mediators, such as IL-6 and TNF-α, were shown to be markedly increased in CIRCI associated with septic shock and TBI." (PMID 24131855, 2013).
septic shock (continued). "It has been shown that patients with CS and manifest MOF exhibit similarly high IL-6 levels, as in patients with septic shock." (PMID 22889197, 2012). "It has been shown that patients with CS and multiorgan failure (MOF) exhibit concentrations of IL-6 of the same magnitude as do patients with septic shock." (PMID 22889197, 2012). "Only seven patients with septic shock (9.5%) presented with IL-6 concentrations in the three highest quartiles in comparison with 20 (27%) for PSP/reg." (PMID 22748193, 2012). "We investigated the predictive value of the mediators IL-6, IL-8, sELAM-1 and sICAM-1 and their time course in intensive care unit patients who developed septic shock with respect to outcome." (PMID 16137344, 2005). "IL-6, a multifunctional cytokine, initiates acute-phase reactions, enhances leukocyte recruitment, and increased vascular permeability, all of which can contribute to tissue damage and organ dysfunction in septic shock." (PMID 40510342, 2025). "First, in septic shock, a secondary analysis of the Vasopressin and Septic Shock trial suggested that higher baseline levels of IL-3, IL-6, and CCL4 may identify patients as potential responders to glucocorticoids resulting in reduced mortality." (PMID 38441708, 2024). "A study on the levels of inflammatory factors in the early stage of septic shock showed that the level of IL-6 in patients with septic shock was significantly higher than that in nonseptic patients, and IL-6 was an independent risk factor for septic shock." (PMID 38813035, 2023). "In the present study, IL-6 levels in the initial blood samples obtained from patients with septic shock significantly decreased in the recovery group but increased among the death group, which suggests that IL-6 levels can be used to monitor the effectiveness of treatment for septic shock." (PMID 31718563, 2019). "This tmTNF-α antibody significantly inhibited LPS-induced secretion of interleukin (IL)-1β, IL-6, interferon-β, and nitric oxide by monocytes/macrophages, and protected mice from septic shock induced by lipopolysaccharide (LPS) or cecal ligation and puncture, while reducing the bacterial load." (PMID 31383857, 2019). "Moreover, IL-6, which is an important mediator of the systemic inflammatory response in septic shock, is produced at a higher level in the culture supernatants of SECepi stimulated T cells." (PMID 29584685, 2018). "Neutralization of extracellular histones with mCBS was associated with reduced norepinephrine requirements, improved tissue perfusion, less renal dysfunction, and lower circulating IL-6 in experimental septic shock and may represent a new therapeutic approach to be tested in clinical trials." (PMID 38001494, 2023). "Finally, patients who developed septic shock showed altered immune status compared to patients who did not develop septic shock, with sustained low HLA-DR/monocytes from D2 to D28 and high serum levels of IL-6, IL-10, and IL-17 at late time points." (PMID 33737924, 2021). "Septic shock is a prevalent condition that, when not lethal, often causes disturbances in cognition, mood, and behavior, particularly due to central actions of the inflammatory cytokine interleukin-6 (IL-6)." (PMID 19284588, 2009). "Weigand and colleagues already described that ICAM-1 may exhibit the ability to predict mortality in septic shock, whereas endotoxin, IL-6, and other different circulating adhesion molecules (e.g. soluble L-selectin, soluble P-selectin, soluble E-selectin) failed to be of prognostic value." (PMID 19538738, 2009). "Baseline IL-6 levels were positively correlated with the SOFA score (Rho = 0.236, p-value = 0.005) and the presence of septic shock (Rho = 0.182, p-value = 0.03)." (PMID 40264754, 2025).
septic shock (continued). "GCS, SOFA score, APACHE 2 score, lactate, CRP, procalcitonin, PRO-ADM, IL-6, CD64 level and 28-day mortality were evaluated in patients with septic shock followed-up in the intensive care unit of Marmara University Hospital between July 2021 and December 2021." (PMID 37592204, 2023). "APACHE II score, IL-6, Lac, TBil, NSE (day1 and day4) showed a weak positive correlation with ICU mortality in patients with septic shock." (PMID 36221401, 2022). "The septic shock group (n = 22) revealed a higher number of male subjects, CRP, IL-6, IL-8 and IL-10 levels, while lower TG, HDLc, monocyte numbers and M/H ratio at admission compared to the non-shock group (n = 27)." (PMID 36368184, 2022). "•Septic shock group showed lower TG, HDLc, monocytes and M/H ratio and higher CRP, IL-6, IL-8 and IL-10 levels at admission." (PMID 36368184, 2022). "As a predictor of the persistence/development of septic shock on the third day of observation (n = 28), the highest AUCs were found for PCT (0.766, 95% CI 0.665–0.867) and IL-6 (0.707, 95% CI 0.595–0.819)." (PMID 29282483, 2018). "Other factors including septic shock, ARDS, day 1 levels of IL-1β, IL-6, IL-8 and CRP, and day 1 SOFA and APACHE II scores, were also predictive of 60-day mortality." (PMID 28542440, 2017). "A second serum module (BS3), which included IL6, IL8, IL10, IP10, GCSF, and MCP1, was elevated in patients with septic shock, ALI, and ECMO-death, in two independent cohorts." (PMID 29163498, 2017). "Because septic shock is mediated by proinflammatory cytokines, the serum concentrations of cytokines such as TNF and IL-6 after the administration of LPS were examined." (PMID 29038465, 2017). "Among patients with septic shock, survivors usually show a decreasing trend of IL-6 levels, and non-survivors usually show increasing IL-6 levels." (PMID 40136690, 2025). "We found that the plasma levels of IL-6, IL-8, IL-10, and MCP-1 were upregulated in all patients (all P value < 0.001), the septic group (all P value < 0.001), and the septic shock group (all P value < 0.001) compared with those in control groups." (PMID 36721090, 2023). "Our results revealed that the antibody induced LPS resistance of monocytes/macrophages in vitro, showing downregulated LPS-induced production of NO, IL-1β, IL-6 and IFN-β, and conferred protection against LPS and CLP-induced septic shock, manifested as reduced inflammation and increased survival." (PMID 31383857, 2019). "Within the septic shock group, there was a positive correlation between VCAM-1 and Charlson comorbidity score at 1 and 3 month follow-up, and at the 6-month follow-up timepoint, IL-6 was positively correlated with age and negatively correlated with EQ-5D-5L VAS score." (PMID 41180006, 2025). "However, in septic shock patients, the correlation between IFNγ and IL-12 (p70) with CETPI, IL-1β, TNF-α, IL-6, IL-8, and IL-10, were not significant." (PMID 36536294, 2022).